ALB (albumin)
Diseases named in the same sentence as ALB in open-access papers (continued):
Sharing a sentence is not in itself a finding about the gene and the disease.
iron deficiency (49 papers, 2007 to 2026). "The blood albumin levels were found to be influenced by various physiological factors like age, circulating estrogen, loss of blood, as well as iron deficiency." (PMID 40806017, 2025). "Blood test results for the patient showed iron deficiency anaemia, reduced serum albumin, and a raised serum ammonia level with a modified end-stage liver disease (MELD) score of 6 and a Child-Pugh score of 8B." (PMID 39649231, 2024). "s-CRP and ECW% increased the likelihood of nutritional risk, whereas independent biomarkers such as PA and s-albumin ≥ 3.8 g/dL were shown to reduce the risk of nutritional disorders in elderly HD patients." (PMID 38140295, 2023). "The iron-deficiency rate among the women for whom we had an albumin measurement was 20/46 (43.5%), which is similar to or lower than other African cohorts and WHO estimates." (PMID 36235668, 2022). "Nutritional factors such as TBW, ECM, and s-CRP increased the likelihood of nutritional risk while independent predictors such as MM, PA, and s-albumin were shown to diminish the risk of nutritional disorders in ACKD." (PMID 36079906, 2022). "Low selenium concentrations and iron deficiency share to a large extent similar clinical predictors such as inflammation, chronic kidney disease, and lower serum albumin levels." (PMID 33835398, 2021). "Older age, lower levels of albumin, worse kidney function, higher levels of NT-proBNP, and the presence of orthopnea and iron deficiency were established as independent predictors of selenium levels <100 μg/L in patients with worsening HF." (PMID 33835398, 2021). "Low selenium was independently predicted by: older age, lower serum albumin, higher N-terminal pro-B-type natriuretic peptide levels, worse kidney function, and the presence of orthopnea and iron deficiency." (PMID 32825781, 2020). "These include uncontrolled hypertension, iron deficiency anaemia and known hypersensivity to mammalian cell-derived products of human albumin." (PMID 21415945, 2010). "In addition, albumin has been shown to be negatively associated with iron deficiency and is considered a predictor of iron deficiency." (PMID 37513518, 2023). "Moreover, the transferrin/albumin ratio has also been used in iron deficiency diagnosis." (PMID 37513518, 2023). "In contrast, the combined use of s-albumin ≥ 3.8 g/dL and s-CRP < 1 mg/dL was shown to significantly decrease the risk of nutritional disorders by multivariate logistic regression analysis in our study." (PMID 38140295, 2023). "The biomarkers conventionally used for suspected CD are decreased hemoglobin (Hb) due to iron deficiency, elevated C-reactive protein (CRP), erythrocyte sedimentation rate (ESR) and lowered plasma albumin (Alb)." (PMID 35956250, 2022). "As further measures, this study used standardized Mediterranean anthropomorphic data and BIA-derived measurements together with nutritional-inflammatory markers such as s-albumin, and s-CRP as recognized risk indicators for nutritional disorders in ACKD." (PMID 36079906, 2022). "Reinforcing the possibility of the occurrence of absorptive/nutritional disorders in MM, we evaluated which metabolites correlate with the albumin drop." (PMID 33318510, 2020). "So patients from the control group were theoretically more prone to develop metabolic and nutritional disorders, as shown by the lower proportion of patients with normal serum phosphate and albumin levels at dialysis initiation." (PMID 23425313, 2013). "However, our study provided a comprehensive approach to BIA measurements together with nutritional and inflammatory markers such as s-albumin, and s-CRP as recognized risk indicators for nutritional disorders in dialysis." (PMID 38140295, 2023). "It should be highlighted that low s-albumin may reflect not only a nutritional disorder but also inflammation and overhydration." (PMID 38140295, 2023).
iron deficiency (continued). "Hashimoto and Koga found that higher HbA1c levels in pregnant women without DM and prediabetes were largely affected by iron deficiency compared with nonpregnant women, but glycated albumin (GA) levels were not affected by iron content." (PMID 35111221, 2022). "Furthermore, inflammation is one of the major conditions contributing to nutritional disorders and is inversely related to s-albumin concentration." (PMID 36079906, 2022). "Protein energy malnutrition (PEM), which is evaluated using the serum albumin value and non-protein respiratory quotient (npRQ), is a well-known nutritional disorder in cirrhotic patients." (PMID 38138202, 2023). "In addition, changes in HbA1c concentration over the entire range of albumin concentrations may be a physiological rather than a pathological association, since the negative association between HbA1c and albumin was not affected by iron deficiency, or poor vascular or renal permeability to albumin." (PMID 34055818, 2021).
cervical cancer (47 papers, 2016 to 2026). A primary or metastatic malignant neoplasm involving the cervix. "For instance, in cervical cancer patients, serum albumin levels were found to be a significant risk factor for prognosis." (PMID 40155840, 2025). "Our results showed cervical cancer-specific deaths associated with occupation, histopathological grading, stage, neutrophil granulocyte, lymphocyte, serum albumin, surgery, radiotherapy, chemotherapy and targeted." (PMID 37064678, 2023). "Prospective clinical trials in patients with organ metastatic cervical cancer using an albumin-based risk assessment are expected in the future." (PMID 36054114, 2022). "Our study demonstrated that preoperative RDW/albumin was an independent risk factor for intraoperative transfusion in patients who underwent radical hysterectomy for cervical cancer." (PMID 36399446, 2022). "Albumin-CRP ratio is a known biomarker for cervical cancer progression, which supports the association between ICC and PhenoAA in our study." (PMID 35570901, 2022). "Similar to the reports on other malignancies, the present results suggest that there is a strong association between pretreatment serum albumin and the prognosis of cervical cancer patients." (PMID 36054114, 2022). "Low serum albumin levels were associated with a low nutritional index and predicted a poor prognosis in a cohort of 131 cervical cancer patients treated with RT or CRT." (PMID 34830902, 2021). "Nevertheless, several biomarkers such as CRP and albumin were found to be associated with shorter survival in patients with cervical cancer, suggesting inflammatory reactions of the body to affect the individual’s oncological outcome." (PMID 30737542, 2019). "Zhang W, Liu K, Ye B, Liang W, Ren Y. Pretreatment C‐reactive protein/albumin ratio is associated with poor survival in patients with stage IB‐IIA cervical cancer." (PMID 29924500, 2018). "This suggests that preoperative RDW/albumin might be a strong risk factor for transfusion and surgical outcomes in cervical cancer patients." (PMID 36399446, 2022). "Therefore, we evaluated the association between preoperative RDW/albumin and intraoperative transfusion and surgical prognosis in patients who underwent radical hysterectomy for cervical cancer." (PMID 36399446, 2022). "In conclusion, preoperative RDW/albumin might be a significant risk factor for intraoperative transfusion and mortality in patients who underwent radical hysterectomy for cervical cancer." (PMID 36399446, 2022). "Moreover, C-reactive acute phase protein (CRP), an inflammatory marker, and serum albumin levels indicative for liver function and malnutrition were associated with impaired immune response in cervix cancer patients." (PMID 34830902, 2021). "Therefore, PLR and albumin were useful prognostic biomarkers that, when combined, provided additional risk stratification for cervical cancer patients." (PMID 26885692, 2016). "In this research, albumin was found as a significant predictor of treatment results for cervical cancer patients under the age of 50." (PMID 41522516, 2026). "Albumin-bound paclitaxel combined with lobaplatin has a significant effect on interventional chemoembolization of cervical cancer." (PMID 40980366, 2025). "This study used albumin-bound paclitaxel combined with lobaplatin to treat cervical cancer patients." (PMID 40980366, 2025). "Our research revealed that higher NLR and elevated albumin levels predict a greater risk of mortality, and a higher NLR was associated with higher chances of recurrence in cervical cancer patients who underwent primary treatment with CCRT." (PMID 39411608, 2024). "This study aimed to assess the efficacy and safety of nanoparticle albumin-bound paclitaxel (nab-paclitaxel) plus platinum versus paclitaxel plus platinum as first-line therapy in patients with metastatic or recurrent cervical cancer." (PMID 38914827, 2024).
cervical cancer (continued). "Serum ALB and HGB are common serum biochemical indicators, which can effectively reflect the nutritional status of patients with cervical cancer and are associated with the development of patients’ disease." (PMID 37875880, 2023). "We report the efficacy and safety of serplulimab, a novel humanized anti–programmed death-1 antibody, plus nanoparticle albumin-bound (nab)-paclitaxel in previously treated patients with programmed death ligand-1 (PD-L1)–positive advanced cervical cancer." (PMID 37153587, 2023). "The results further indicated that ALB and HGB levels were also important risk factors affecting the prognosis of patients with early cervical cancer in addition to traditional risk factors." (PMID 37875880, 2023). "We investigated the relationship between ALB and HGB levels and clinicopathologic characteristics of early-stage cervical cancer to determine the influence of ALB and HGB on the prognosis of early-stage cervical cancer." (PMID 37875880, 2023). "Some studies have also shown that the C-reactive protein /ALB ratio was closely related to the prognosis of cervical cancer." (PMID 37875880, 2023). "In conclusion, in the present patient series, the malnourished patients (albumin ≤3.3 g/dL) with organ metastatic cervical cancer had shorter survival than those with albumin >3.3 g/dL." (PMID 36054114, 2022). "In the second-line treatment of cervical cancer, camrelizumab combined with albumin-bound paclitaxel has been used in a study of recurrent or persistent advanced cervical cancer patients after first-line chemotherapy (NCT05290935)." (PMID 36387196, 2022). "We conducted the present study to determine the prognostic impact of the albumin value in patients with metastatic cervical cancer." (PMID 36054114, 2022). "A previous study reported that plasma albumin values differed significantly amongpatients with cervical cancer." (PMID 36794669, 2022). "We retrospectively analyzed the cases of patients with metastatic cervical cancer to investigate the significance of pre-treatment albumin for the prediction of overall survival." (PMID 36054114, 2022). "The univariate and multivariate analyses revealed that pretreatment serum albumin and mode of primary treatment were significantly associated with survival in patients with stage IVB cervical cancer." (PMID 36054114, 2022). "In this study, we showed that ICA treatment was significantly upregulated the spleen and thymus index, as well as the levels of ALB in U14 cervical cancer mouse models." (PMID 33849528, 2021). "Reports of CRP level in relationship to blood albumin level (i.e. the CRP/albumin ratio) as a novel prognostic index for survival for cervical cancer have appeared." (PMID 33324413, 2020). "Serum albumin levels, CRP, neutrophils, and platelet counts, for instance, seem to be associated with tumor stage and survival in patients with cervical cancer." (PMID 30737542, 2019). "Consistent with previous studies, we showed that decreased albumin was associated with poor OS and DFS in operable cervical cancer patients." (PMID 26885692, 2016). "Currently, this is the largest study of the prognostic roles of preoperative PLR and albumin in cervical cancer." (PMID 26885692, 2016). "In this research, from this CR potential, investigate in vitro the effect of photodynamic therapy induced by Cherenkov emission by the hybrid nanostructure of graphene oxide-albumin-surfactant-protoporphyrin (GBCP: GO-BSA-CTAB-PpIX) on It was performed on cervical cancer cells." (PMID 40896695, 2025). "There was a statistically significant difference in the occupation, histopathological grading, stage, neutrophil granulocyte, lymphocyte, serum albumin, surgery, radiotherapy, chemotherapy and targeted in the cervical cancer-specific mortality group (p < 0.05)." (PMID 37064678, 2023).
cervical cancer (continued). "In other words, even in patients with organ-metastatic cervical cancer, if the albumin level is >3.3, CCRT may be more effective in prolonging life as the initial treatment." (PMID 36054114, 2022). "In previous studies, FAR or AFR (albumin to fibrinogen ratio) was proved to be related to a systemic inflammatory response in various malignant tumors, including but not limited to gastric, esophageal, lung and cervical cancers." (PMID 36109740, 2022). "In addition, lower ALB levels in gastric, rectal, and cervical cancers have also been shown to be prognostic predictors of tumors." (PMID 35663321, 2022). "Hence, we decided to combine CRP and serum albumin to create a new inflammatory prognostic factor in stage IB‐IIA cervical cancer." (PMID 29193777, 2018). "However, few studies have investigated the relationship between preoperative albumin and patient survival in cervical cancer." (PMID 26885692, 2016). "This study aims to design an albumin-based photosensitive hybrid nanostructure (GBCP: GO-BSA-CTAB-PpIX) in order to maximally absorb the emitted photons from Cherenkov radiation in a wider wavelength range and increase the efficiency of free radical conversion caused by PDT on cervical cancer cells." (PMID 40896695, 2025). "RDW/albumin might be a significant factor in transfusion and mortality in cervical cancer patients." (PMID 36399446, 2022). "In cervical cancer treatment, neutrophil-to-lymphocyte ratio (NLR), platelet-to-lymphocyte ratio (PLR), and albumin-globulin ratio (AGR) are being studied as potential prognostic markers for predicting the effectiveness of concurrent chemoradiotherapy (CCRT)." (PMID 39411608, 2024). "Nanoparticle albumin-bound (nab)-paclitaxel is one such chemotherapeutic option, recording the highest ORR (28.6%) when given as a single agent against drug-resistant cervical cancer compared with other chemotherapies." (PMID 37153587, 2023). "The purpose of this study was to investigate the role of preoperative lymphocytes, albumin, neutrophils, and LANR in the prognosis of patients with stage IB-IIA cervical cancer (CC)." (PMID 37729271, 2023). "Coupled with the evidence above, previously reported associations between PhenoAge components, including serum glucose, albumin, and C-reactive protein (CRP), and cervical cancer also support the biological plausibility of our study." (PMID 35570901, 2022). "We aimed to evaluate the association between preoperative red cell distribution width/albumin ratio (RDW/albumin) and transfusion in cervical cancer patients." (PMID 36399446, 2022). "We developed a novel cervical cancer systemic inflammation score (CCSIS) based on the preoperative platelet-to-lymphocyte ratio (PLR) and serum albumin levels." (PMID 26885692, 2016). "Both albumin levels and the PLR were independent prognostic indicators for operable cervical cancer." (PMID 26885692, 2016). "We also developed a novel prognostic score, the cervical cancer systemic inflammation score (CCSIS), based on preoperative serum albumin levels and PLR." (PMID 26885692, 2016). "In conclusion, this study highlights the potential role of PLR and albumin as prognostic factors for OS and DFS in early-stage cervical cancer patients." (PMID 26885692, 2016). "In addition to ALB, studies have also shown that HGB levels affect the prognosis of patients with cervical cancer." (PMID 37875880, 2023). "Therefore, it is vital to detect the ALB and HGB levels of patients and improve the nutritional status of patients in a timely manner to improve the prognosis of patients with cervical cancer." (PMID 37875880, 2023). "Thus far, there are few studies on the relationship between ALB and HGB level and prognosis of early cervical cancer." (PMID 37875880, 2023). "Therefore, it is of great significance to detect the ALB and HGB levels of patients and improve the nutritional status of patients in a timely manner for better prognosis of cervical cancer." (PMID 37875880, 2023).
cervical cancer (continued). "Since stage IVB accounts for less than 10% of cervical cancer, it was inferred that serum albumin is unlikely to be revealed its function as a prognostic factor." (PMID 36054114, 2022). "Our objective was to review a single institution experience in treating recurrent, refractory cervical cancer with nano-particle albumin bound (NAB) paclitaxel with or without bevacizumab." (PMID 27231575, 2016). "Accordingly, inflammation-based prognostic indicators, such as the modified Glasgow Prognostic Score (mGPS), platelet to lymphocyte ratio (PLR), neutrophil to lymphocyte ratio (NLR), albumin, and C-reactive protein (CRP) are prognostic factors for cervical cancer as well as other cancers." (PMID 26885692, 2016). "In addition, levels of C-reactive protein (CRP) and albumin (ALB), among circulating inflammatory proteins closely related to systemic nutritional status, are valuable prognostic indicators for many malignancies, including cervical cancer." (PMID 37729271, 2023). "A phase II clinical study (NCT04150575) investigated HLX10 (a new anti-PD-1 antibody) combined with albumin and paclitaxel as second-line therapy for advanced cervical cancer or patients with advanced cervical cancer who could not tolerate toxicity." (PMID 36817443, 2023). "So far, no studies have explored the links between PLR and serum albumin in cervical cancer." (PMID 26885692, 2016).